LAG3 (lymphocyte activating 3)
Diseases named in the same sentence as LAG3 in open-access papers (continued):
Sharing a sentence is not in itself a finding about the gene and the disease.
tumor (continued). "Some preclinical data have shown that the combination of PD-1 and LAG-3 blockade can enhance anti-tumor cytotoxic T-cells activity and reduce tumor growth in a MPM model." (PMID 36902544, 2023). "We noticed that the expression levels of all checkpoints under investigation, except LAG-3, increased on monocytes derived from tumor-bearing lungs compared to healthy controls." (PMID 35493461, 2022). "A series of other checkpoints such as programmed cell death protein-1 (PD-1), programmed cell death-ligand 1 (PD-L1) and lymphocyte activation gene-3 (LAG-3) have also been identified to promote tumor immune escape and tumorigenesis." (PMID 35757741, 2022). "Another study revealed that LAG-3 correlates with glucocorticoid-induced TNF receptors across multiple tumor types." (PMID 36077354, 2022). "Chemotherapy affected the expression levels of LAG-3 and PD-1, which ultimately mediated tumour immune escape." (PMID 35494015, 2022). "(vii) FS118, a bispecific antibody against PD-L1 and LAG-3, has been confirmed to enhance the activation of T cells in mouse tumour models, bringing about potent antitumour activity." (PMID 35494015, 2022). "(i) Both LAG-3 and PD-1 were observed on T cells in the tumour microenvironment in animal models of mouse MC38 colorectal adenocarcinoma and SalN fibroma." (PMID 35494015, 2022). "Lymphocyte activation gene 3 (LAG-3), also known as CD223, is a single-pass transmembrane glycoprotein and is an immune checkpoint receptor associated with tumor escape and decreased T cell effector function." (PMID 36233269, 2022). "We additionally found a switch in the expression of specific immune checkpoints, with an increase in the Ctla-4 and Lag3 lymphocyte co-inhibitory responses, and in the Icosl co-stimulatory responses of tumour cells." (PMID 36433941, 2022). "Applying allogeneic γδ T cell transfer in combination with LAG3 checkpoint blockade should potentially maximise the anti‐tumour function of γδ T cells in HCC immunotherapy, which should be tested in future work." (PMID 35390227, 2022). "In order to better understand the underlying mechanisms that were responsible for enhanced anti-tumor activities in the MWA combined with the LAG3 blockade group, we checked the proportions of TILs in the tumors from different groups." (PMID 36180876, 2022). "Preclinical and early clinical trials have indicated that active LAG3 promotes tumor cell immune escape." (PMID 36278613, 2022). "Authors have shown interaction between LAG3 and its receptor FGL1 can cause changes in the tumour microenvironment, such as reduction in IL-2 levels, disrupting anti-tumour immunity." (PMID 35625783, 2022). "Our analysis does clearly indicate that the expression of LAG-3 is a robust marker for Tregs retained within the tumor, and the data presented here provide a new resource to help define the Treg compartment of tumors." (PMID 35472220, 2022). "The expression of immune checkpoints including programmed cell death protein 1(PD-1), lymphocyte-activation gene 3 (LAG-3), cytotoxic T-lymphocyte-associated protein 4 (CTLA-4) on tumor-infiltrating CD4+ T cells was reduced as well." (PMID 35774793, 2022). "Further studies into LAG3’s role in Treg function are required to elucidate the mechanisms behind its variable activity in the tumor and autoimmune settings." (PMID 35345849, 2022). "IHC analysis for CD8+LAG3+ cells between para-Tumor and Tumor suggested that CD8+LAG3+ T cells potentially acted as the key exhaustion T cell marker in nccRCC (all p < 0.05)." (PMID 35017463, 2022). "The discovery of immune checkpoints, such as PD-1, CTLA-4, LAG-3, and TIM-3, has shifted the cancer treatment paradigm by targeting cancer itself to modulate a tumor-associated immune response." (PMID 36077619, 2022). "Twenty-one days after cell transfer, both tumor-infiltrating T cell populations expressed PD-1, Lag-3, Tim-3 and TIGIT (relative to naïve T cells in the spleen)." (PMID 35264436, 2022).
tumor (continued). "LAG-3 blockade is currently being investigated in clinical trials, either as monotherapy or combined with the inhibition of other ICs, to treat multiple tumor types." (PMID 35164813, 2022). "PD1 and LAG3 are commonly co-expressed on anergic peripheral T-cells, and simultaneous blockade can reverse T-cell anergy and enhance anti-tumor activity." (PMID 35954384, 2022). "The tumor lysates induced a greater T-cell response in MM patients’ BMMC (N = 5) than irradiated whole tumor cells, which was enhanced to a greater extent by checkpoint inhibitors (anti-LAG3 > anti-PD1) than by immune agonists (anti-OX40, anti-GITR)." (PMID 34290359, 2022). "LAG-3 is widely expressed in different tumor types and modulates the tumor microenvironment through immunosuppressive effects." (PMID 36077354, 2022). "In cancer, LAG-3 expressing Tregs accumulate at distinct tumor sites, thereby suppressing cytotoxic T cells." (PMID 36135216, 2022). "Considering the high degree of intra-tumoral heterogeneity present in RCC, we took advantage of the multiple replicates analyzed in TMAs-166 and -528 to first assess the correlation in LAG3 protein counts across replicate cores for the same tumor specimen." (PMID 36313654, 2022). "Although not statistically significant, the αTIGIT + bintrafusp alfa combination treatment doubled the population of PD-1+LAG3+ CD8+ T cells infiltrating the tumor." (PMID 36211806, 2022). "Interaction of immune checkpoint molecules like CTLA-4, LAG-3 or PD-1 with their ligands B7.1/B7.2 on antigen-presenting cells, fibrinogen-like protein-1 and Galectin-3 or PD-L1 on tumor cells, respectively, enhance immune escape of tumor cells." (PMID 36700232, 2022). "Some studies have demonstrated improvement in anti-tumor immunity by inhibiting the PD-L1 and LAG-3 simultaneously using bispecific antibodies." (PMID 35967381, 2022). "SPI1 expression was positively and strongly associated with T cell exhaustion markers (LAG3 and PDCD1,), and Treg cell markers (FOXP3 and CCR8), suggesting that high SPI1 expression level inhibits anti-tumor immunity." (PMID 36477668, 2022). "LAG3 suppresses anti-tumor immunity directly by TCR downregulation, and also indirectly by impeding CD4+ T-cell functions via competitively binding to MHC II with a higher affinity." (PMID 36211375, 2022). "They found that TILs in the tumor region had increased levels of both LAG-3 and PD-1 suggesting the apparent synergy and benefit of dual checkpoint blockade therapy in NSCLC." (PMID 36059606, 2022). "Nonetheless, with these conflicting reports in mind, it is unclear what role, if any, LAG-3 plays if expressed on tumour cells." (PMID 35265944, 2022). "As in the case of B16F10-OVA, ablation of nociceptors decreased the growth of tumours and reduced their frequency in intratumoral PD-1+LAG3+TIM3+ CD8 T cells." (PMID 36323780, 2022). "Higher LAG3 levels have been observed in RS neoplastic and tumor-infiltrating lymphocytes, suggesting its potential role in promoting tumor immune escape and neoplastic cell survival." (PMID 36230566, 2022). "CD4+ T cells-expressed LAG-3 binds to the MHC class II complex on antigen-presenting cells, while CD8+ T cells-expressed and NK cells-expressed LAG-3 links to the LSECtin on tumor cells or liver cells." (PMID 35978433, 2022). "More importantly, FCGR3A expression positively correlated with immune checkpoint molecules, including PD1, PD-L1, PD-L2, CTLA4, LAG-3 and TIM-3, and tumor-associated macrophage (TAM) gene markers in LGG." (PMID 39280892, 2022). "Intriguingly, when FGL1/LAG3 and PD-1/PD-L1 axes were simultaneously inhibited, the therapeutic effect was significantly improved, evidenced by a longer lifespan and reduced tumor burden in mice." (PMID 34975333, 2022). "In the tumor killing experiment of PBMC in vitro, YG-003D3 has a better ability to activate PBMC to kill tumor cells than anti-PD-1 or anti-LAG-3 single drug group or even combined drug group, and the killing rate is as high as 20%." (PMID 36518768, 2022).
tumor (continued). "So, inhibiting LAG-3 enhances the immune system’s anti-tumor function by improving the effectiveness of other types of immunotherapy." (PMID 35967381, 2022). "In tumor tissues, LAG-3 is usually expressed in T cells with lost functions, called exhausted T cells." (PMID 35135556, 2022). "However, it is less clear whether LAG-3 glycosylation is associated with tumor immunity." (PMID 36558902, 2022). "Tumor-associated double positive expanded clonotypes frequently displayed a Tem phenotype and expressed elevated exhaustion markers PDCD1, TIM3, LAG3 and CTLA4 similar to tumor-restricted CD8+ expanded clonotypes." (PMID 36185254, 2022). "LAG-3 is regarded as a prospective therapeutic target for tumor immunotherapy since several studies have demonstrated a correlation between high levels of LAG-3 expression with tumor growth and prognosis in a variety of human tumor types." (PMID 36558902, 2022). "In vulvar squamous neoplasia LAG-3+ tumor-infiltrating lymphocytes were identified in 91% of cases and its enhanced level was observed with GAL-3 co-expression." (PMID 36077354, 2022). "LAG3 and TIGIT, two classical ICPs, were detected in tumor-infiltrating lymphocytes and showed a prominent association with other ICPs." (PMID 36246963, 2022). "Ag-specific CD8 T cells newly recruited into the tumor expressed minimal levels of PD-1, LAG-3, and CD39 alongside reduced amounts of Granzyme B compared with the retained populations." (PMID 35472220, 2022). "Models show that FGL-1 inhibits the antigen-specific activation of CD8+ T-cells and the blockade of FGL-1/LAG-3 interaction stimulates tumor immunity." (PMID 36140182, 2022). "Liver tissue of the DEN/CCl4-treated Cxcl10−/− mice displayed the same level of Lag3 in the surrounding and tumor tissue." (PMID 35897689, 2022). "As measured on day 13, BIBN4096 (5 mg kg−1, i.p., every other day) reduced B16F10 growth, tumour weight and frequency of PD-1+LAG3+TIM3+ CD8+ T cells." (PMID 36323780, 2022). "The attention over other immune checkpoints increased significantly in the last years, and new potential targets were identified, such as Lymphocyte-activation gene 3 (LAG3), which is highly expressed on tumor-infiltrating lymphocytes (TILs)." (PMID 36013315, 2022). "Several studies confirmed that LAG-3 expression is increased in tumor-infiltrating lymphocytes relative to liver background in patients with HCC." (PMID 36077354, 2022). "In the present study, we treated mice with MWA or LAG3 blockade and phenotyped their anti-tumor immune responses in a mouse colon cancer MC38 model." (PMID 36180876, 2022). "A stepwise increase in the expression of all of these molecules was observed over time, such that CD8 T cells retained within the tumor for at least 72 h robustly expressed PD-1, LAG-3, CD39, and the highest level of Granzyme B." (PMID 35472220, 2022). "Conditional cDC1 depletion significantly decreased splenic Klrg1+ and intratumoral Lag3+ tumor-specific T cell frequency." (PMID 35393950, 2022). "LAG-3 was significantly upregulated on the surface of tumour-infiltrating CD4+ T cells compared with those in circulation in the treatment-naïve setting and post-FLOT setting (p = 0.01 and p = 0.007)." (PMID 35366537, 2022). "One study found that blocking both LAG-3 and PD-1 promoted T cell-mediated immune responses leading to a significant delay in tumor growth compared to anti-PD-1 antibody or anti-LAG-3 (LBL-007) treatment alone in CRC model mice." (PMID 35911673, 2022). "Immune checkpoints such as PD1, PD-L1, CTLA-4, and LAG3 are important in tumorigenesis, which can promote tumor immunosuppressive effects." (PMID 36160009, 2022). "Tumor cells can evade T cell-mediated killing by upregulating the interaction of ligands (such as PD-L1) with the inhibitory receptor PD-1, CTLA-4, and LAG-3, which are expressed on tumor-infiltrating T-cells." (PMID 35281003, 2022).
tumor (continued). "Further analysis of the association between the Tumor Recurrence Factor risk score and common immune checkpoints of tumors showed that the Tumor Recurrence Factor risk score was correlated with CD47, CTLA7, HAVCR2, LAG3, PDCD1, and other immune checkpoints." (PMID 35677036, 2022). "We will also summarize results achieved by other LAG-3 targeting molecules with promising anti-tumor activities currently under clinical development in phases I, I/II, II, and III." (PMID 35954196, 2022). "We found that FoxP3 expression and ICs including PD-1, CTLA-4, TIM-3, and LAG-3 were significantly increased in tumor-infiltrating CD8+ T cells compared with NT and peripheral blood." (PMID 35804964, 2022). "In a humanized PD-1/LAG-3 transgenic mouse subcutaneous tumor-bearing model, YG-003D3 showed good anti-tumor activity, even better than that of the combination group at the same molar concentration." (PMID 36518768, 2022). "When comparing anti-tumor activity between the anti-4-1BB/anti-PD-1 and the anti-PD-1/anti-LAG-3 in the B16-F10 melanoma mouse model, tumor regression occurred in animals receiving anti-PD-1 anti-4-1BB was more concomitantly." (PMID 35585567, 2022). "Both CAR MUC1 T cells significantly upregulated TIM3 and LAG3 expression after coculture with tumor cells." (PMID 36457849, 2022). "High-level expression of multiple inhibitory receptors such as PD-1, LAG3 and TIM-3 on CTLs have been associated with a hyporesponsive state in which anti-tumor responses become ineffective." (PMID 34228218, 2022). "Ieramilimab, an IgG4 mAb anti-LAG-3, has been evaluated in combination with spartalizumab (mAb anti-PD-1) in a phase II study enrolled patients with different tumor types including SCLC relapsed or refractory to standard therapies." (PMID 36551630, 2022). "The tribodies containing the anti-PD-1 or anti-LAG-3 scFv (53D and 53G) showed up to the 60–70% of tumor cells lysis and those with the anti-PD-L1 scFv (53L1 and 53L10) led to 80–90% of tumor cell lysis." (PMID 36071464, 2022). "Previous studies have confirmed that FGL1 is the main ligand of LAG-3 and its function of inhibiting the anti-tumor T cells by binding to it." (PMID 35273912, 2022). "What’s more, the results of combination therapy showed that compared with PD-1 antibody therapy alone, the expression of PD-L1 and LAG3 in tumor tissues were markedly decreased, and the expression of CTLA-4 was significantly increased." (PMID 36160005, 2022). "To explore mechanism of GIMAP4 underlying tumor-immune regulation, we calculated the correlations between GIMAP4 and 5 ICPs (CD274, CTLA4, TIGIT, LAG3, and PDCD1) and identified similar trends in their expression." (PMID 36246963, 2022). "The success of Sym023 promoted the studies evaluating the preliminary efficacy of the combined Sym021 (anti-PD-1), Sym022 (anti-LAG-3), and Sym023 in tumor therapies (NCT04641871 and NCT03311412)." (PMID 35978433, 2022). "LAG-3 is expressed on activated tumor-infiltrating lymphocytes (TILs) (for example CD4 and CD8 positive T-cells, T-regs and B-lymphocytes), and it regulates T-cell function as an inhibitory ICP." (PMID 36289918, 2022). "The percentage of exhausted CD4+ T cells, described as TIM3+LAG3+, was reduced in spleens and pulmonary tumors by depletion of tumor cell–autonomous SHP2." (PMID 36969745, 2022). "It was observed that simultaneous blockage of LAG-3 activity and anti-PD-1 or PD-L1 in tumor cells has dual inhibitory effects, including inhibiting Treg activity, promoting dendritic cells (DCs) maturation, and rescuing dysfunctional CD4+/CD8+ T cells." (PMID 35958563, 2022). "The clinical significance of LAG-3 in LPS remains largely undefined, as to our knowledge only one study showed that high levels of LAG-3 were associated with high tumor grade and shorter OS in a mixed STS cohort." (PMID 36230502, 2022).
tumor (continued). "In this study, we assessed LAG3 expression in tumor infiltrating leukocytes on matched normal kidney and primary RCC cases, and matched primary and metastatic RCC cases, including brain metastases." (PMID 36313654, 2022). "Blocking LAG-3 activity and anti-PD-1 or PD-L1 in tumor cells has dual inhibitory effects, including inhibiting Treg activity, promoting DC maturation, and rescuing dysfunctional CD4+/CD8+ T cells." (PMID 35958563, 2022). "LAG-3 is expressed on several subsets of tumor-infiltrating lymphocytes such as activated CD8+ T cells and Treg cells, as well as on myeloid-derived suppressor cells." (PMID 35328630, 2022). "The tumor infiltrating T and NK cells had significantly elevated expression levels of LAG-3, PD-1, and HLA-DR compared to the circulating immune cells." (PMID 35003893, 2022). "As a new immune checkpoint receptor, LAG-3 plays a vital role in immune homeostasis maintenance and tumour immune escape and is widely present in various activated immune cells." (PMID 35494015, 2022). "Isolated LAG3 blockade showed very limited anti-tumor activity, while combined with other ICIs such as PD-1 inhibitors, it offers promising results." (PMID 36139683, 2022). "LAG3-targeted immunotherapies have been tested as an important anti-tumor agent in lots of clinical trials for multiple types of cancer." (PMID 36180876, 2022). "Beyond CTLA-4 and PD-L1/PD1, one target that is actively being studied is the lymphocyte activation gene-3 (LAG-3), which has been associated with the exhaustion of tumour-infiltrating T cells, as a mechanism of resistance to certain immunotherapies." (PMID 36297474, 2022). "Responding patients trended towards having higher levels of immune gene expression, including CD8 and LAG3, in tumor tissue at baseline." (PMID 35217575, 2022). "The 63 upregulated genes, including PLA2G2D, IFNG, LAG3, CD8B and NKG7, were associated with tumor immunity." (PMID 35530341, 2022). "A number of reports have expounded that the combinatorial blockade of LAG-3 and PD-1 pathways synergistically enhance anti-tumour immunity in some solid tumours." (PMID 36297474, 2022). "Tumour-infiltrating lymphocytes expressing elevated levels of LAG3 have been found in solid tumours such as ovarian cancer, melanoma, and colorectal cancer, as well as Hodgkin’s and diffuse large B-cell lymphoma." (PMID 36551617, 2022). "Tregs cells expressing LAG-3 can suppress tumor-specific T cells and produce high levels of the immunoregulatory cytokines interleukin (IL)-10 and transforming growth factor-beta (TGF-β)." (PMID 36225938, 2022). "Collectively, these data afford new insight into how tumor-infiltrating Treg phenotypes change over time, with LAG-3 expression identifying Tregs that become retained within this environment." (PMID 35472220, 2022). "The treatment with each checkpoint inhibitor also increased anti-tumor activities of XBP1/CD138/CS1-CTL against MM cells, evidenced by increased CD107a degranulation and IFN-γ production, with the highest anti-tumor activities induced by anti-LAG3 treatment." (PMID 34290359, 2022). "Analysis of LAG-3 expression in the TCGA dataset revealed a wide expression range in various tumor types." (PMID 36077354, 2022). "LAG-3 maintains the body’s immune homeostasis under physiological conditions while mediating tumour immune escape." (PMID 35494015, 2022). "Triple PD-1/TIM-3/LAG-3 blockade has been proposed to overcome this barrier in syngeneic mouse tumor models, but in our hands triple blockade was less effective than dual PD-1/LAG-3 blockade." (PMID 36605214, 2022). "Our results support that cDC1s are required for the reactivation of tumor-specific memory T cells, resulting in their differentiation into the Klrg1+Lag3– effector subset, which appear critical for tumor control." (PMID 35393950, 2022).